GIMAP1 (GTPase, IMAP family member 1)
Description:
May regulate lymphocyte survival. Required for normal levels of mature T-lymphocytes and mature B-cells (By similarity).
Synonyms: hIMAP1; IMAP1; IMAP38; IAN2
Tractability: Small molecule: a structure with a bound ligand is known. Antibody: UniProt predicts a signal peptide or a membrane-spanning region. PROTAC: ubiquitination databases record sites on it; its protein half-life has been measured.
Gene: Protein-coding gene on chromosome 7 (150,716,606 to 150,724,284, forward strand). Ensembl gene ENSG00000213203.
Subcellular location: Endoplasmic reticulum membrane; Golgi apparatus membrane
Subcellular location (Human Protein Atlas): Endoplasmic reticulum
Gene Ontology:
Molecular function: protein binding; GTPase activity; GTP binding
Cellular component: endoplasmic reticulum; endoplasmic reticulum membrane; Golgi membrane
Genetic constraint (gnomAD): Loss-of-function variants: 1 observed, 10.03 expected, observed/expected ratio (o/e) 0.0997, 90% interval 0.034 to 0.47. The synonymous counts are far from expectation, so gnomAD's model fits this gene poorly and the ratio says little. Missense variants: 423 observed, 410.78 expected, observed/expected ratio (o/e) 1.03, 90% interval 0.95 to 1.12. Synonymous variants: 230 observed, 187.38 expected, observed/expected ratio (o/e) 1.23, 90% interval 1.1 to 1.37.
Homologues: Orthologues: macaque GIMAP1 (87% identical), rat Gimap1 (62% identical), mouse Gimap1 (61% identical), dog GIMAP1 (58% identical), guinea pig GIMAP1 (57% identical). Paralogues in human: GIMAP6 (39% identical), GIMAP5 (38% identical), GIMAP2 (37% identical), GIMAP4 (34% identical), GIMAP7 (31% identical), GIMAP8 (29% identical), GIMD1 (17% identical).
Diseases named in the same sentence as GIMAP1 in open-access papers:
GIMAP1 is named in the same sentence as 22 diseases in open-access papers, as found by Europe PMC text mining. Sharing a sentence is not in itself a finding about the gene and the disease. The quoted sentences say what the papers report.
breast carcinoma (4 papers, 2022 to 2025). "Meanwhile, GIMAP1, as a member of some novel gene signatures, can predict prognosis in pancreatic cancer, endometrial cancer, and breast cancer." (PMID 35860577, 2022). "Another bioinformatic analysis on GIMAP family members indicated that GIMAP7 together with GIMAP1, GIMAP5, GIMAP6, and GIMAP8, are lowly expressed in breast cancer tissues." (PMID 38151913, 2024). "Bioinformatics show GIMAP1, GIMAP5, GIMAP6, GIMAP7, and GIMAP8 are downregulated in breast cancer." (PMID 40535419, 2025).
lymphopenia (4 papers, 2009 to 2018). Reduction in the number of lymphocytes. "Genetic deficiencies in either GIMAP5 or GIMAP1 produce severe peripheral lymphopenias in rodent models." (PMID 24204963, 2013). "To determine whether the T‐cell lymphopenia in GIMAP1‐deficient mice also exhibits an age‐dependent profile, we enumerated CD4+ T cells in Gimap1f/fCD2Cre+ and control Gimap1f/f mice at 5 and 10 weeks of age." (PMID 27792288, 2017). "Therefore, the sequence analysis of Gimap1 and Gimap3 supports the hypothesis that Gimap5 is the cause of lymphopenia in the DR.lyp/lyp rat." (PMID 19421422, 2009). "This possibility has been strengthened by genetic and cellular studies of the lymphopenias and cell death associated with GIMAP5 and GIMAP1 deficiencies which cast doubt on the involvement of the BCL2-related apoptotic machinery in the lymphopenias." (PMID 29718959, 2018). "Our previous study of GIMAP1 in Gimap1f/fCD2Cre+ mice had analysed T‐cell numbers in 10–12 weeks old mice 21, a time point by which any age‐dependent onset of lymphopenia may have already occurred." (PMID 27792288, 2017). "T‐cell numbers in GIMAP1‐deficient mice were profoundly reduced by 5 weeks of age suggesting that the lymphopenia in GIMAP1‐deficient mice is not age‐dependent." (PMID 27792288, 2017). "Gimap4 and Gimap1 each had one amino acid substitution of unlikely significance for lymphopenia." (PMID 19421422, 2009). "Aside from Gimap5, only Gimap1 and Gimap3 could potentially play a role inthe development of lymphopenia, as they are the only remaining genes locatedwithin the 33 Mb interval critical for lymphopenia between D4Rhw6 andIIsnp3." (PMID 19421422, 2009).
lung carcinoma (3 papers, 2020 to 2025). "The survival analysis of the GIMAP family was performed, and the results showed that high levels of GIMAP1, GIMAP2, GIMAP4, GIMAP5, GIMAP, GIMAP7 and GIMAP8 mRNA expression levels were associated with better overall survival of patients with lung cancer." (PMID 34604035, 2021). "GIMAP1/4/6/7/8 were predicted to have a higher association with LUAD filtered by RNA expression in this study, while GIMAP2 was predicted to have an association with lung carcinoma and GIMAP2 was predicted to have an association with sepsis." (PMID 33115964, 2020). "Incorporating five predictive variables—gender, nodule size, CST1, and GIMAP1-GIMAP5—into a binary logistic regression model, we aimed to predict the probability of lung cancer." (PMID 40535419, 2025). "The under- expression of GIMAP1/2/4/5/6/7/8 were found in lung cancer tissues consistently, while neither GIMAP3 nor GIMAP1-GIMAP5 presented available data." (PMID 33115964, 2020).
autoimmune disease (2 papers, 2021). A disorder resulting from loss of function or tissue destruction of an organ or multiple organs, arising from humoral or cellular immune responses of the individual to their own tissue constituents. "GIMAP1 has been commonly reported to be related to autoimmune diseases, such as Bechet’s disease and type I diabetes." (PMID 33901011, 2021).
endometrial cancer (2 papers, 2022). Primary or metastatic malignant neoplasm involving the endometrium (mucous membrane that lines the endometrial cavity). "GIMAP1 is crucial for the survival of B cells used as the major marker of endometrial cancer." (PMID 35782114, 2022).
lymphoma (2 papers, 2021). A malignant (clonal) proliferation of B- lymphocytes or T- lymphocytes which involves the lymph nodes, bone marrow and/or extranodal sites. "Moreover, GIMAP1 is reported to be downregulated in lymphomas and regulates the B and T lymphocyte cell cycle." (PMID 33901011, 2021).
pancreatic cancer (2 papers, 2021 to 2022). "In this study, a four-gene prognostic signature that included SPINK1, ANO1, DSG3, and GIMAP1 in patients with pancreatic cancer were identified." (PMID 33901011, 2021).
anaplastic large cell lymphoma (1 paper, 2021). Anaplastic large cell lymphoma (ALCL) is a rare and aggressive peripheral T-cell non-Hodgkin lymphoma, belonging to the group of CD30-positive lymphoproliferative disorders, which affects lymph nodes and extranodal sites. "The expression of GIMAP5 occurs in many T cell leukemic cell lines and in anaplastic large cell lymphoma (ALCL) cell lines while the expression of GIMAP1, GIMAP2, GIMAP6 and GIMAP7 were down-regulated in ALCLs." (PMID 34135906, 2021).
B cell lymphoma (1 paper, 2009). "GIMAP1 was not expressed in all of the cell lines tested but was found at significant levels in C1498, an NKT cell line, TK-1 (thymoma) and A20 cells (B cell lymphoma), and at a lower level in P815 cells (mastocytoma)." (PMID 19338674, 2009).
cervical cancer (1 paper, 2022). A primary or metastatic malignant neoplasm involving the cervix. "Finally, we identified that the model constructed by GIMAP4, GIMAP1, FGF13-AS1, EFEMP2, and DYNC2I2 could be used as the prediction model for the prognosis of cervical cancer." (PMID 35782114, 2022).
COVID-19 (1 paper, 2025). A disease caused by infection with severe acute respiratory syndrome coronavirus 2. "Future studies should include non-COVID-19 GGN cohorts to validate whether CST1 and GIMAP1-GIMAP5 serve as pandemic-unrelated biomarkers or are influenced by COVID-19-associated lung inflammation." (PMID 40535419, 2025).
diffuse large B-cell lymphoma (1 paper, 2021). "GIMAP1 expression is increased in diffuse large B-cell lymphoma (DLBCL) due to hypomethylation of the GIMAP locus." (PMID 34135906, 2021).
lung adenocarcinoma (1 paper, 2025). A carcinoma that arises from the lung and is characterized by the presence of malignant glandular epithelial cells. "Specifically, CST1 was upregulated, whereas GIMAP1-GIMAP5 was downregulated in lung adenocarcinoma tissue when contrasted with normal tissue." (PMID 40535419, 2025). "Our study found lower GIMAP1-GIMAP5 expression in malignant nodules and linked it to shorter survival in lung adenocarcinoma patients, indicating its clinical importance for diagnosis and prognosis in this disease." (PMID 40535419, 2025). "Among the downregulated genes, only GIMAP1-GIMAP5 showed decreased expression in lung adenocarcinoma tissues." (PMID 40535419, 2025). "Upon intersecting with the datasets GSE118370 and GSE140343, we identified that CST1 and GIMAP1-GIMAP5 were the only genes exhibiting significant differential expression in lung adenocarcinoma tissue compared to normal tissue." (PMID 40535419, 2025). "In summary, CT imaging and RNA sequencing analysis of benign and malignant nodules, combined with a nomogram, suggest that CST1 and GIMAP1-GIMAP5 are potential biomarkers for lung adenocarcinoma of GGNs, providing new insights into its pathogenesis and treatment." (PMID 40535419, 2025). "Finally, we validated the clinical significance of CST1 and GIMAP1-GIMAP5 in patients with lung adenocarcinoma, particularly highlighting a strong correlation between GIMAP1-GIMAP5 expression levels and prognosis for patients." (PMID 40535419, 2025). "With no existing research on GIMAP1-GIMAP5's link to lung adenocarcinoma, our initial findings suggest the necessity for further studies to explore their role and impact on the disease's progression." (PMID 40535419, 2025).
malaria (1 paper, 2009). Malaria is a serious and sometimes fatal disease caused by a parasite that commonly infects a certain type of mosquito which feeds on humans. "GIMAP1 was originally discovered in a differential screen of a spleen cell cDNA library made from malaria (Plasmodium chabaudi)-immune mice using cDNA from immune or non-immune mouse spleens." (PMID 19338674, 2009). "This contrasts with the high level of GIMAP1 mRNA expression attributed to macrophages in malaria-immune spleen by Krücken and colleagues." (PMID 19338674, 2009). "It had previously been reported that GIMAP1 expression, measured at the mRNA level, was elevated in the spleens of mice with malaria." (PMID 19338674, 2009). "The initial aim of this investigation was to generate antibodies specific for mouse GIMAP1, in order to study the expression of this GTPase at the protein level and learn more about the nature of the cells expressing it in both naïve and malaria-immune or -infected mice." (PMID 19338674, 2009). "Our studies of GIMAP1 have forced a reconsideration of the conclusions drawn previously about the role that this gene may be playing in a favoured mouse model of malaria." (PMID 19338674, 2009).
tumor (3 papers, 2021 to 2025). "The mRNA expression of SPINK1, DSG3, ANO1 were significantly increased in PAAD tumor tissue while GIMAP1 were significantly decreased compared with normal tissues." (PMID 33901011, 2021). "In the perspective of tumor grade, GIMAP1 showed the lowest expression in high grade while GYPC showed the lowest expression in G3." (PMID 33869285, 2021). "The downregulated gene GIMAP1, with a hazard ratio (HR) < 1, was regarded as a tumor suppressor, while the upregulated genes ANO1, DSG3, and SPINK1, with a HR > 1, were considered oncogenes." (PMID 33901011, 2021). "Downregulation of GIMAP1-GIMAP5 may disrupt immune surveillance in the tumor microenvironment, potentially impairing T-cell function or promoting immune evasion, which could accelerate tumor progression and worsen prognosis." (PMID 40535419, 2025). "We observed that higher tumor grade of EC was accompanied by lower GIMAP1 expression and it seemed that higher grade of EC might have less functional lymphocytes infiltration in EC tumor microenvironment and led to a worse prognosis." (PMID 33869285, 2021). "The expression levels of GIMAP1 and GYPC were significantly correlated to the tumor grade and only GYPC was significantly correlated to the tumor histology in EC." (PMID 33869285, 2021).
cancer (1 paper, 2025). A tumor composed of atypical neoplastic, often pleomorphic cells that invade other tissues. "We also found an increase expression of Gimap1/3/4/5/6/7/8/9, genes which encode for GTPase IMAP (immunity-associated proteins) family members that have been implicated in cancer progression through the regulation of immune cell infiltration." (PMID 39523394, 2025). "This was accompanied by a decrease in gene expression of cancer related genes (Myc, Axin2, Gimap1/6/8)." (PMID 39523394, 2025).
infection (1 paper, 2009). The state of being infected such as from the introduction of a foreign agent such as serum, vaccine, antigenic substance or organism. "It was also used to assess the expression of GIMAP1 protein after infection and/or immunization of mice with P. chabaudi." (PMID 19338674, 2009). "The model of up-regulation of GIMAP1 in response to infection/immunization with P. chabaudi is not a robustly reproducible experimental system." (PMID 19338674, 2009). "Surprisingly, no up-regulation of GIMAP1 expression was seen at either the mRNA or protein level, irrespective of the virulence of the parasite or number of parasites used for infection." (PMID 19338674, 2009). "Various other combinations of erythrocyte ghost treatment from infected or naïve mice, and infection or immunization with vehicle were tried and no treatment was found to significantly up-regulate GIMAP1." (PMID 19338674, 2009). "GIMAP1 expression, which was relatively weak in naïve mouse spleen, was increased two to 30-fold post infection in various mouse strains on the C57BL/10 or C57BL/6 backgrounds and was high in spleens of immune mice both pre- and post-infection." (PMID 19338674, 2009). "GIMAP1 was also not up-regulated in either male or female mice on days 4, 7 or 12 of infection." (PMID 19338674, 2009).
GIMAP1 also shares sentences with these, for which no sentence is quoted: Autoimmunity (1 paper); mastocytoma (1); Sepsis (1); thymoma (1); type I diabetes (1).